IL10 (interleukin 10)
Diseases named in the same sentence as IL10 in open-access papers (continued):
Sharing a sentence is not in itself a finding about the gene and the disease.
infection (continued). "Unlike in the CLN, IL-10 is down-regulated in both brain and spleen of the mice 7 days post infection, suggesting a possible absence of a balancing regulatory response in these tissues and increasing the likelihood for the development of a certain degree of pathology." (PMID 38912206, 2024). "Thus, we observed no significant changes in IFN-γ, TNF-α, and IL-10 expression between the two groups with double infection." (PMID 38790916, 2024). "To characterize the impact of IFNγ and IL-10 blockade on immune responses to SARS-CoV-2 infection, we analyzed transcriptional profiles of BAL cells isolated at baseline and days 3, 7, 14 and 28/35 after infection using Nanostring transcriptomics (n = 752 immune response genes)." (PMID 38950078, 2024). "Mice of all groups were euthanized on the 6th day post-infection, and the intestine of each was isolated for parasitological, histopathological, and immunohistochemistry evaluation of MMP-9, as well as assessment of cytokines level (IFN-γ and IL-10 gene expressions) via Real-time PCR technique." (PMID 39421828, 2024). "As opposed to this, IL-10 haplotypes had no clear link with the infection." (PMID 38790226, 2024). "Moreover, it is believed that the production rate of IL-10 and both IFN-γ and TNF-α by human CD4+ T cells, and the regulated shift from one to the other during the course of infection, are crucial for the development of an appropriate but self-limiting immune response." (PMID 38787228, 2024). "At 24 hours and 72 hours after infection, significant increases in the frequency of both IL-17–producing Th17 and IFN-γ–producing Th1 cells were observed in the peritoneal cavity of mice that were immunized with the vaccine + anti–IL-10 compared with control groups." (PMID 38973612, 2024). "With regard to Th2 and Treg cytokines, infection did not induce a statistical difference in the production of IL-4 or IL-10 when compared to that in the healthy group (IL-4: p > 0.1022; IL-10: p > 0.3939)." (PMID 39598539, 2024). "Compared to the non-infection group, we observed elevated levels of the majority of measured cytokines (25/48) in the CSF during Mtb infection, including TNF-α, IFN-γ, IL-1β, IL-2, IL-3, IL-6, IL-8, IL-10, IL-12(p40), IL-17A, IL-18, IP-10, MIG, MCP-3, MIP-1α, and MIP-1β." (PMID 38047697, 2024). "In TBM, anti-inflammatory cytokines such as IL-10 and TGF-β play a critical role in regulating the immune response, preventing excessive inflammation, and modulating the differentiation and activation of immune cells to ensure an appropriate immune response to the infection." (PMID 38047697, 2024). "In the present work, it was also observed that infection of mice with a UPEC strain activated the expression of TNF-α; however, the administration of a polyvalent bacterial lysate (UNAM-HIMFG) controlled both colonization and inflammation (activating the expression of IL-10) of the tissues." (PMID 39337365, 2024). "Indeed, the parental strains do not manifest phenotypic features of MMTV infection, but infection emerges in the absence of IL-10." (PMID 36869359, 2023). "At week 4 post infection, CD4+ T-cells showed a mixed response to S. mansoni AWA by secreting cytokines which encompassed Th1 (IFNγ, TNFα, IL-2 & IL-1β), Th2 (IL-4, IL-5, IL-13) and regulatory responses (IL-10) as well as the regulatory T cell transcription factor Foxp3." (PMID 37837930, 2023). "The level of the anti-inflammatory cytokine IL-10 was not significantly affected by the infection." (PMID 37615937, 2023). "Furthermore, in IL-10-/- BMDMs derived from IL-10-/- mice, the CXCL13 protein concentration was significantly decreased compared that in wild-type BMDMs after FMDV infection (FMDV-Wild type group vs. FMDV-IL-10-/- group: 2158.0 ± 257.7 vs. 1175.1 ± 113.7 pg/mL, respectively, n = 3, p < 0.05)." (PMID 37047294, 2023).
infection (continued). "IFN‐γ, IL‐10, and IL‐23 release measured by multiplex were significantly lower in patients who developed a subsequent infection compared to those who did not (115 vs 27 IU/mL, P = 0.037; 457 vs 202 pg/mL, P = 0.008; and 1039 vs 663 pg/mL, p = 0.01, respectively)." (PMID 37125245, 2023). "CD8, γδ-T cells (positive for γδ-TCR and γδ-WC1), NKp46, TNF-α, FoxP3, and IL-10 cell labelling were significantly lower in NC than in DL, and the estimated differences between the NC group and the three infection groups were generally similar, though not consistently statistically significant." (PMID 37375536, 2023). "In addition, some studies found that the levels of IL‐2, IL‐4, IL‐6, IL‐7, IL‐10, IP‐10, MCP‐1, TNF‐α, MIP‐1α, IFN‐γ, and G‐CSF in patients with severe COVID‐19 infection were significantly higher than those in patients with mild and moderate infection." (PMID 36684101, 2023). "However, treatment of C. jejuni 81-176 infection of germ-free IL-10−/− mice with deoxycholic acid below the MIC did not decrease densities but ameliorated some disease manifestations." (PMID 38164399, 2023). "No significant changes in IL-10 levels were observed between all four infection groups." (PMID 37305417, 2023). "However, several critical cytokines (IL-4 and IL-10) of the Th2 response have opposite killing effects on protoscoleces by elevating the levels of NO, which enhances the cytotoxic effect in C57BL/6 mice upon infection." (PMID 37637465, 2023). "In turn, its absence confirms the loss of macrophage activation despite a more severe inflammatory process that, even with greater tissue severity compared with WT animals, lacks the degrees of necrosis and pyroptosis observed with infection in the absence of IL10 and extreme macrophage activation." (PMID 37228668, 2023). "After the vaccination of sheep and goats with an IL-10 gene deficient LSDV recombinant and subsequent challenge infection, no viraemia could be detected in the vaccinated animals either." (PMID 37112675, 2023). "About 60% of the second transfer cells produced IL-17 in the absence of IL-10 on day 8 post infection, compared to 25% in the setting with IL-10, and the IL-17 production of the second transfer cells was linked to the protection against influenza virus infection in IL-10KO mice." (PMID 37270623, 2023). "Interestingly, unlike CRP, serum levels of PCT, IL-6, and IL-10 in the GN-BSI group were consistently higher than those in the GP-BSI group at all time points during 48 h post-infection." (PMID 37986183, 2023). "Importantly, it was also observed that in the absence of TLR2 and the resulting IL-10, neonatal neutrophils were able to migrate to infected lungs and control infection." (PMID 37375099, 2023). "These cells were initially characterized as CD138+IL10+ cells that exhibited increased expression of the inhibitory receptors LAG3, CD200, PD-L1, and PD-L2 as compared to CD138+IL10- cells and were the predominant source of IL-10 produced in response to infection." (PMID 38155972, 2023). "We found a higher frequency of IL-10+ Treg in unstimulated or Pool CoV-2-stimulated Mild Recovered PBMC compared to that in HC and Severe Recovered groups, strengthening the hypothesis of persistent immune changes after the resolution of infection." (PMID 36969257, 2023). "However, at 24 h of infection with persister cells, a bi-modal trend was present in IL-6 and CXCL-8 with an overall increase in secretion, compared to 1.5 h, while IL-10 was at levels identical to uninfected macrophages." (PMID 36920189, 2023). "As we previously reported that the infection of macrophages is closely related to their inflammatory state, we investigated the expression of three inflammatory cytokines, TNF, IL1 and IL6, and one immunoregulatory cytokine, IL10, by MDMs and PMs infected with C. burnetii using qRT-PCR." (PMID 36674725, 2023).
infection (continued). "The analysis of the mean expression of cytokines during the infection process showed that the simultaneous injection of two bacteria together with the Leishmania led to a significant decrease in the expression of IFN-γ, IL-1β and IL-10 compared to the control group (P<0.0001)." (PMID 36779192, 2023). "Interestingly, levels of pro-inflammatory cytokines reduced as time passed from the beginning of infection, while IL-7 and IFN-γ and IL-10 tended to increase, showing the recovery of a more functional immune system and of mechanisms to counterbalance inflammation." (PMID 36675231, 2023). "Pro-inflammatory (IFNγ, IL-6, TNFα), Treg (IL-10, TGFβ1, TGFβ3), Th9 (IL-9), Th17 (IL-17), and Th2 (IL-4, IL-13) cytokines, total IgM and IgG, as well as gene expressions of FoxP3, STAT5+, IFNγ-R1, and ROR alpha+, were measured at day 1, day 7, day 14, day 21, and day 28 post-infection." (PMID 37569646, 2023). "Furthermore, the infection also encourages macrophages to secrete pro- and anti-inflammatory cytokines such as tumor necrosis factor-α (TNF-α), interleukin-1β (IL-1β), IL-6, interferon-γ (IFN-γ) and IL-10." (PMID 37280772, 2023). "Additionally, the anti-inflammatory cytokine IL-10 was not significantly induced during S. salivarius single-infection or during dual infection." (PMID 37305417, 2023). "Similarly, ESBL-EAEC infection elevated transcription levels of IL-1β, IL-6 and TNF-α in colonic tissues, but recovered after GA administration with an obvious decline of IL-10 and TGF-β." (PMID 35399688, 2022). "Taken together, these results suggest that the host SUMOylation process favors the infection and survival of L. donovani in macrophages by modulating the levels of pro-inflammatory cytokines such as TNF-α, IFN-γ, IL-12p40, and IL-32γ and anti-inflammatory cytokine, IL-10." (PMID 35734580, 2022). "In addition, the levels of type II cytokines such as IL-4, IL-13, and IL-10 in infected wild-type mice were significantly higher than in the control mice without infection (P < 0.05)." (PMID 36271450, 2022). "Since we observed lower IL‐10 levels in the spleen and lung of Sema3E-Fc treated mice and Treg is one of the primary sources of this cytokine, we next examined CD4+ CD25+ Foxp3+ T cells in the lungs of WT and Sema3E KO mice treated with Sema3E-Fc following Cm infection." (PMID 35983029, 2022). "Additionally, as infection-related non-relapse mortality is an uncommon complication, experienced by only 15/315 (5%) of patients in this study, sample size within IL-10-1082 genotype subgroups was not amenable to a formal statistical comparison." (PMID 36555525, 2022). "Similarly, E. coli 1587 infection elevated the transcription levels of IL-1β, IL-6, TNF-α, and IL-10 in the colonic tissues, while TGF-β was decreased." (PMID 35643532, 2022). "The M1 response was higher during LdCen-/- infection, compared to WT L. donovani infection, and was characterized by the upregulation of inflammatory mediator transcripts (IL-1β, IL-12, TNF-α, and iNOS2) and the downregulation of M2-related genes (IL-10, YM1, Arg-1, and MRC-1 genes)." (PMID 35456106, 2022). "Others, such as IL-1α, IL-2, IL-7, IL-9, IL-10, IL-12p40, IL-13, and VEGF were present at equivalent concentrations in lungs of infected and control mice during the first 5 days, but at significantly reduced concentrations in lungs of infected mice at day 7 post-infection." (PMID 35812400, 2022). "Interestingly, although no decrease in IL-10 was detected, we found a lower parasite load in monocytes between 4 and 24 h of infection in the presence of pioglitazone." (PMID 35909958, 2022). "This study reveals that the healing efficacy of G. mangostana crude extract was achieved by reducing the expression of antioxidant genes (CAT, SOD, and GPx) and inflammatory cytokine genes (TGF-β, TNF-α, IFN-γ, and IL-10) to levels similar to those of the no infection group." (PMID 35369604, 2022).
infection (continued). "Similarly, E. coli 1587 infection dramatically stimulated the upregulation of IL-1β, IL-6, IL-10, and TNF-α mRNA transcription levels in mice colons 3 days post infection, but this phenomenon mostly diminished by 7 days post infection except for IL-6." (PMID 35399688, 2022). "IL-10, IL-7, and IFN-γ all maintained a stable expression over time and could be playing a role in longer-term immunity, but IL-1RA, MIP-1α, IL-4, TNF-α, and more were all significantly decreased one-year post-infection compared to levels at discharge." (PMID 35406717, 2022). "Therefore, IL-4 and IL-10 may play an important role in PTB, characterized by infection and inflammation." (PMID 35860261, 2022). "Moreover, IL-10 deficiency increased CD4+T cells and CD8+T cells but not macrophages in the liver of mice with infection." (PMID 36310865, 2022). "In addition, we also found that the mRNA transcript levels of pro-inflammatory cytokines IL-1β, TNF-α, IL-6, and IL-12, and anti-inflammatory cytokines IL-4, and IL-10 tended to decrease (p < 0.05 or p < 0.01) in the cats from the feIFN-ω’ treatment group, compared with the FPV infection group." (PMID 35068319, 2022). "They further suggested that IL-10 and GBP1 might inhibit the activation of caspase-3 and lead to the attenuation of macrophage apoptosis, thereby fostering the intracellular survival of mycobacteria and establishment of infection." (PMID 35773466, 2022). "The higher concentrations of IL-8, IP-10 and TNFα (proinflammatory response) when compared to IL-4 or IL-10 (anti-inflammatory response) suggested a induction of proinflammatory response due to the infection in these TB-infected animals, regardless of the study group." (PMID 36439353, 2022). "Several infection studies described a negative correlation between secretion of IL-10 and survival." (PMID 35215216, 2022). "Since previous studies support IL10 as a key player in the establishment and perpetuation of HIV persistence, the upregulation of IL10 in CXCR3+TFH may result in enhanced persistence of HIV after infection." (PMID 35619703, 2022). "While IFNγ, IL-4, IL-10, and IP-10 did not seem to directly correlate with antibody response amongst our cohorts, they were elevated in moderate and severe COVID-19 disease, compared to mild infection." (PMID 36865568, 2022). "To investigate whether a similar immune response characterized by diminished induction of Th2 cytokines could also be found at the infection site, we measured the percentages of CD4+IFN-γ+, CD4+IL-10+, and CD4+IL-4+ T cells in the challenged ears of control and vaccinated mice at 10 wpc." (PMID 35236861, 2022). "For those plasma cytokines and chemokines with no sex-specific differences over the course of infection, a majority, including IL-2, IL-10, IFN-γ, MIP-1α, IL-3, IL-4, IL-5, IL-12p70, IL-13, IL-17, and G-CSF, exhibited differing temporal patterns between genotypes." (PMID 35970557, 2022). "By showing that IL-10 overexpression during the chronic stages of the infection does not impact control of infection, our data demonstrate that the reduced migration of CD4+ T cells to the lung parenchyma is the critical mechanism whereby IL-10 antagonizes control of Mtb infection." (PMID 35935958, 2022). "Since our data indicates at 60 days post-infection in old SDR mice there is increased IL-10 mRNA levels in the lungs, we next examined whether CD4+ T cells in the lungs of these mice have the phenotype of IL-10 producing regulatory T cells." (PMID 36189368, 2022). "In fact, endogenous IFNs-I are commonly present in hepatopathic livers and Kupffer cells are particularly responsive to IFNs-I, by producing IL10 and inhibiting IL1 production and inflammasome activation, which could make the liver further permissive to parasitism during early infection." (PMID 35154115, 2022).
infection (continued). "The present study, revealed the significant up-regulation of pro-inflammatory cytokines, such as, IL-1β, IL-6, IL-10, IFN-γ and non-significant elevation of TNF in infected controls on the 9th day post-infection, showing an association with disease severity that supports previous findings." (PMID 36510199, 2022). "Interestingly, infected Lgals3–/– mice showed a drop in serum levels of Th1 and Th2 cytokines, including IFN-γ, IL-2, IL-5, IL-6, IL-10, and TNF, compared with WT mice; these differences were significantly pronounced at 14 days but ceased at 28 days post-infection." (PMID 35046919, 2021). "Then, when there are no other clear laboratory indicators to indicate infection, one should be alert to the abnormal increase of IL-6, IL-8 and IL-10, which may indicate bacterial infection in the lungs." (PMID 34925324, 2021). "The mRNA level of IL-4 was absent while IL-10 occurred during the later phase of infection." (PMID 33680991, 2021). "For instance, studies demonstrate that as the levels of IL-10 increased in the PBMC of patients with LCL, TNF-α also increases, maintaining a balance between the two responses, which is not only necessary for controlling infection but also for preventing immunopatholgy." (PMID 34169006, 2021). "The animals were sacrificed 96 hours and 2 weeks after infection, their lungs removed, macerated and the leukocytes analyzed by flow cytometry for the intracellular expression of IDO, AhR, and cytokines (IL-12, TNF-α, IL-1β, IL-6, TGB-β, and IL-10) by CD11c+ myeloid cells." (PMID 33936043, 2021). "After single infection with H3N2, an elevated mRNA expression of pro-inflammatory cytokines TNF and IFN-γ (mean fold change of 2.22 and 1.86, respectively), and anti-inflammatory cytokines IL-10 and TGF-β (mean fold change of 1.92 and 2.40 respectively), was observed." (PMID 34858411, 2021). "On day four post-infection, the levels of pro-inflammatory cytokines TNF-α and IFN-γ were decreased to 6.6 and 2.5 times that observed in controls respectively while the levels of anti-inflammatory cytokine IL-10 and IL-4 were increased (by 2.1 and 5.7 times) upon quercetin treatment." (PMID 33803419, 2021). "However, in CF sera, we showed a marked increase in IL-10 levels (p < 0.05), independent of infection." (PMID 34475490, 2021). "The results of cytokine secretion showed that although the percentages of IL-4-, IL-10-, and IL-12-secreting DCs from WT mice increased significantly after infection (P < 0.05), no marked difference was found between infected WT and infected TLR7 KO mice (P > 0.05)." (PMID 34692568, 2021). "However, as infection progresses, C57BL/6 macrophages could have been able to downregulate Il10 expression, shifting towards an M1 phenotype." (PMID 33617537, 2021). "Remarkably, we found higher TNF, IL-1β, IL-6, and IL-10 in lung homogenates of LysM-cre × Hif1αfl/fl mice when compared with Hif1αfl/fl control mice at 12 hours after inoculation; these differences were not present anymore at 40 hours after infection." (PMID 34393650, 2021). "Moreover, EBN restores the immune system in the context of infection by influencing viruses through regulation of pro-inflammatory cytokines, such as IL-6 and TNF-α, and cytokines with regulatory properties, such as IL-10 and CCL2, which are also involved in the progression of UC." (PMID 33967768, 2021). "Low amounts of IL-10 produced during subclinical infection may serve as negative feedback to limit Th1-induced inflammation without compromising host cell parasite killing abilities." (PMID 34827938, 2021). "We therefore hypothesized that IL-10 would antagonize control of M. tuberculosis infection by impairing the translocation of CD4+ T cells into the lung parenchyma, where they could interact with infected phagocytes to induce control of infection." (PMID 34554927, 2021).